IL6 (interleukin 6)
Diseases named in the same sentence as IL6 in open-access papers (continued):
Sharing a sentence is not in itself a finding about the gene and the disease.
pemphigus (14 papers, 2008 to 2025). Pemphigus is a group of rare autoimmune diseases that cause blistering of the skin and mucous membranes (mouth, nose, throat, eyes, and genitals).This conditioncan occur at any age, but often strikes people in middle or older age. "It is thus intriguing that the increase of Flavonifractor and positive correlation between Flavonifractor and circulating inflammatory markers (C5a, IL-6, IL-8, IL-7, IL-1β and IL-21) were reported in pemphigus vulgaris, a subgroup of pemphigus." (PMID 38022583, 2023). "TNF-α, IL-6, IFNs, IL-17, IL-21, and IL-23 among others are known for their contribution to inflammatory process also in the course of pemphigus." (PMID 32170648, 2020). "TNF- α, IL-6, IL-15, IL-10, IL-12, are involved in the mechanism of pemphigus lesions formation." (PMID 36613766, 2022). "Finally, specific inflammatory cytokines like interleukin-6, shown to be increased in both serum and blister fluid of pemphigus patients, are essential for KS tumorigenesis." (PMID 18605999, 2008). "Furthermore, polymorphisms of genes encoding several cytokines, such as IL-4, IL-6, IL-10, TNF-α, and transforming growth factor-β have been reported in pemphigus patients compared to healthy controls, suggesting a potential involvement in the pathogenesis of this disease." (PMID 38213911, 2023). "We investigated the plasma concentrations of the APC-derived immunomodulatory cytokine IL-27 and the pro-inflammatory cytokines IL-6 and TNF-α in active and remitting pemphigus patients, MG patients and HC." (PMID 26872212, 2016). "Likewise, several studies have reported increased levels of IL-8, IL-6, and TNF-α in pemphigus, which were also in the ceRNA network." (PMID 34531933, 2021). "Presence of a chronic inflammatory background may represent a link between pemphigus, cardiovascular comorbidities and a lower overall survival, due to the direct involvement of various cytokines, such as TNF alpha and IL-6." (PMID 25896794, 2015). "The plasma levels of IL-6 were not increased in active pemphigus and MG, respectively." (PMID 26872212, 2016). "Interestingly, in the remitting pemphigus patients (n = 3) neither IL-27 nor IL-6 or TNF-α could be detected in distinct amounts." (PMID 26872212, 2016).
pertussis (14 papers, 2006 to 2025). A contagious bacterial respiratory infection caused by Bordetella pertussis. "For pertussis with compromised seroprotective titers in all the study groups, a significant association with gestation age, monocyte, and plasma levels of IL-6, IL-10, and IL-2 was found in univariate analysis, but plasma IL-6 levels emerged to be the significant parameter in multivariate analysis." (PMID 33968011, 2021). "IL-6 is known to play a significant role in mounting an immune response to infection with B. pertussis and vaccination against pertussis." (PMID 37917623, 2023). "Despite identifying role of IL-6 in generating adequate anti-pertussis antibody response, the question of less efficacy of the vaccine even in term infants remains unanswered." (PMID 33968011, 2021). "Our current in vivo study demonstrated that immunization with an OMV-based pertussis vaccine (omvPV) in comparison to wPV elicited reduced concentrations of serum pro-inflammatory cytokines (IL-1α, IL-1β, and IL-6), chemokines (CXCL1 and CXCL10), and G-CSF." (PMID 27905535, 2016). "After whole cell pertussis vaccine immunization, serum levels of IL-6 and IL-12p70 were very low in C3H/HeJ mice." (PMID 21203418, 2010). "After whole cell pertussis immunization of the TLR4-deficient C3H/HeJ mice, IL-6 and IL-12p70 were almost undetectable in the serum." (PMID 21203418, 2010). "Furthermore, we did not observe the vast changes in cytokine responses in this model that have been observed in mouse and baboon models of pertussis, such as IL-6 and IL-17." (PMID 34516235, 2021). "Despite this, we nonetheless demonstrate that heterologous IL-1β and IL-6 responses 3 months after BCG vaccination, i.e. at the moment of Tdap-IPV vaccination, but not 2 weeks after BCG vaccination are associated with enhanced pertussis humoral and cellular immunity." (PMID 35177621, 2022). "Furthermore, increases in pertussis antibodies, total IgG-switched MBC responses, and IFNγ in response to PT restimulation in the BCG-trained cohort were associated with innate responses, in particular IL-1β and IL-6." (PMID 35177621, 2022). "For the Pertussis pathway, the main responsible genes for the pathways were CASP3, IL-1β, IL-1, IL-6, TNFα, and iNOS." (PMID 37895148, 2023). "Unlike a parenterally delivered whole-cell pertussis vaccine, which induced high levels of serum IL-1β, IL-6, tumour necrosis factor and C-reactive protein, aerosol immunization with the AIBP vaccine did not promote systemic pro-inflammatory responses." (PMID 41214155, 2025). "Pertussis antigens contained in the Tdap-IPV vaccine have been previously shown to induce cytokine production in vitro; FHA induces TNF-α production in human monocyte-derived macrophages and stimulates the production of IL-10 and IL-6 in mouse macrophages and DCs." (PMID 34649076, 2021). "This differs from a previous study in preterm infants where increased adverse cardiorespiratory events and increased systemic inflammatory markers (IL-6, CRP) occurred in 30% of infants receiving whole cell pertussis vaccine but in no infants receiving acellular pertussis vaccine." (PMID 16784533, 2006).
pneumococcal meningitis (14 papers, 2012 to 2025). An acute purulent infection of the meninges and subarachnoid space caused by Streptococcus pneumoniae, most prevalent in children and adults over the age of 60. "Our previous studies showed an increased expression of the proinflammatory cytokines TNF-α and IL-6 in CRAMP-deficient mice after pneumococcal meningitis." (PMID 27057100, 2016). "Furthermore, pneumococcal meningitis patients with the IRAK4 risk allele had higher levels of IL-6 in their CSF with the diagnostic lumbar puncture, suggesting that these patients have an increased pro-inflammatory response during their disease." (PMID 27432718, 2016). "Also, as expected, IL-6 signalling-mediated inflammation was the cellular process most strongly associated with pneumococcal meningitis." (PMID 26040285, 2015). "TNF-α, IL-1β, and IL-6 are the major pro-inflammatory cytokines with early response in pneumococcal meningitis." (PMID 32238192, 2020). "Next, gene expression levels of the pro-inflammatory cytokines TNF-α or IL-6 as major mediators of the inflammatory reaction during pneumococcal meningitis were determined in the hippocampal formation as well as cortex 28 h after infection." (PMID 33121515, 2020). "This study was designed to determine the role of TNFR1 and IL-6 in a mouse model of pneumococcal meningitis." (PMID 27057100, 2016). "At first, we examined the gene expression of the proinflammatory cytokines TNF-α, IL-6, and IL-1β as representatives of inflammatory mediators in pneumococcal meningitis." (PMID 27057100, 2016). "In previous pneumococcal meningitis models IL-6 was shown to be involved in CSF leukocyte recruitment and possibly in the regulation of blood brain barrier disruption." (PMID 22455545, 2012). "TNF-α, IL-1 and IL-6 are considered to be the early response proinflammatory cytokines that are upregulated early in during pneumococcal meningitis." (PMID 22455545, 2012). "Furthermore, the increased mortality of TNFR1−/− and TNFR1-IL-6−/− mice correlated with decreased glial cell activation compared to IL-6−/− or wild type mice after pneumococcal meningitis." (PMID 27057100, 2016). "We looked at mortality, and CSF cytokine concentrations (IL-6, IL-8, TNFα, IL-10, IL-1β, IFN-γ) in three patients and in a pneumococcal meningitis model." (PMID 36683678, 2022). "Our present findings are congruous with those of Klein and colleagues, who similarly report lesser increases in IL-1β, but comparable concentrations of CCL2 and IL-6, within the brains of TLR2/4 double GKO mice in a pneumococcal meningitis model." (PMID 31700009, 2019). "In our study, we confirm the established role of C/EBPδ as activator of the inflammatory response, reflected by the reduction in IL-10 and KC levels in the brain and IL-6, IL-10, KC, and MIP-2 in plasma during pneumococcal meningitis." (PMID 25958220, 2015). "Whereas, in experimental pneumococcal meningitis model the animals presented, in the first twenty four hours, elevated levels of TNF-α and CINC-1 in the hippocampus and TNF-α, IL-1β, IL-6 and CINC-1 in frontal cortex." (PMID 23548182, 2013). "Therefore, we have determined the mRNA expression of TNFR2 in the hippocampal formation and cortex of TNFR1−/−, IL-6−/−, TNFR1-IL-6−/−, and WT mice after pneumococcal meningitis." (PMID 27057100, 2016). "IL-6 (median 20 versus 795 pg/ml, P < 0.0001), IL-1β (median 165 versus 939 pg/ml, P = 0.014), and RANTES (median 15 versus 1823 pg/ml, P < 0.0001) were increased at 30 hours post infection in mice inoculated with pneumococcal meningitis as compared to saline inoculated mice." (PMID 22455545, 2012). "In the present study, the consequences of lack of TNFR1 and/or IL-6 were investigated in a well-characterized mouse model of pneumococcal meningitis and showed that the lack of both TNFR1 and IL-6 results in increased mortality and higher bacterial burden." (PMID 27057100, 2016).
relapsing-remitting MS (14 papers, 2015 to 2025). "Clinical studies in patients with relapsing remitting-MS (RR-MS) confirmed an association between higher levels of IL-6 in the cerebrospinal fluid (CSF) and a worse disease course characterized by an increased relapse rate and greater disability." (PMID 35627281, 2022). "With this study, we investigated the IL-12/STAT4, IL-23/STAT3, and IL-6/STAT3 pathways in patients with relapsing-remitting MS (RRMS) and the potential impact of genetic background on activation of these pathways." (PMID 30917537, 2019). "For instance, we have recently evidenced that CD28-mediated upregulation of pro-inflammatory cytokines (i.e., IL-8, IL-6, IL-21, and IL-17A) was higher in human primary T lymphocytes from relapsing-remitting multiple sclerosis patients (RRMS) compared with HD." (PMID 28491063, 2017). "Studies performed in humans with relapsing-remitting MS show that IL-6 supports T cell effector function resistance to regulation by Tregs, which may contribute to disease severity." (PMID 33679788, 2021). "The increase of pro-inflammatory cytokines interferon gamma (IFN-γ), tumor necrosis factor alpha (TNF-α) and interleukin 6 (IL-6) prior to and during clinical relapse have been widely demonstrated in the literature in relapsing-remitting MS (RRMS) compared to controls." (PMID 34589733, 2021). "Interleukin 6 (IL-6) represents a major inflammatory molecule previously associated with exacerbated disease activity in relapsing remitting MS (RR-MS); however, the role of single-nucleotide polymorphisms (SNPs) in the IL-6 gene has not been fully elucidated in MS." (PMID 35627281, 2022). "Furthermore, fluoxetine decreased the production of IL‐1β, IL‐6, and IL‐17 by activated CD4+ and CD8+ T-cells, suggesting an anti-inflammatory effect of treatment with fluoxetine on Th17-immune response in relapsing-remitting MS patients with MDD." (PMID 36189272, 2022). "(2021) showed an increase in the levels of IL-6 and IL-1ß in blood plasma in patients with relapsing-remitting MS (n=25) and MDD compared with MS patients without MDD (n=25)." (PMID 36189272, 2022).
respiratory distress syndrome (14 papers, 2013 to 2022). "In a lamb model of infant respiratory distress syndrome, the combination therapy of surfactant and rCC16 lowered IL-8 in serum and IL-6 in the lung tissue more than surfactant therapy alone." (PMID 34768890, 2021). "Moreover, different studies have identified IL-6 as the indicator of disease severity in adults with COVID-19 infections; in particular, non-survival in adults with respiratory distress syndrome (ARDS) was linked to IL-6 and IL-1 increases." (PMID 34578450, 2021).
upper respiratory tract infections (14 papers, 2015 to 2026). "EV-HRV causes upper respiratory tract infections but causes cytokine releases such as IL-1, IL-6, and IL-8 in the lower respiratory tract and in the blood which can cause ARDS." (PMID 35784975, 2022). "Outcomes included reactive oxygen species (ROS; whole-blood EPR), total antioxidant capacity (FRAP), superoxide dismutase (SOD), interleukin-6 (IL-6), tumor necrosis factor-α (TNF-α), and upper respiratory tract infection (URTI) incidence and duration." (PMID 42197007, 2026). "In our earlier meta-analysis of the effectiveness of probiotic supplementation on the upper respiratory tract infection (URTI) and inflammatory markers in elite athletes, we concluded that probiotic supplementation may decrease IL-6 and TNF- levels." (PMID 35807826, 2022).
varicocele (14 papers, 2019 to 2026). A condition characterized by the dilated tortuous veins of the spermatic cord with a marked left-sided predominance. "In thermal stress induced by varicocele, an increase in IL-6 levels over time was observed, as well as progressive testicular damage." (PMID 39021494, 2024). "Studies show that varicocele stimulates the release of proinflammatory and inflammatory cytokines such as interleukin-1 (IL-1), IL-6, IL-8, and tumor necrosis factor-alpha (TNF-α)." (PMID 37476898, 2023). "It has been demonstrated that the semen of varicocele patients contains higher levels of several inflammatory cytokines, such as interleukin (IL)-6, IL-1b, and tumor necrosis factor-alpha." (PMID 37727396, 2023). "Among the other cytokines involved in the testicular tissue during varicocele, IL-6 and tumor necrosis factor-α (TNF-α) play an important pro-inflammatory role." (PMID 36555779, 2022). "This methodology allowed us to highlight that most patients affected by varicocele, infections and men with a history of cryptorchidism belonged to the group characterised by IL-6 level > 21.5 pg/mL." (PMID 33620706, 2021). "The results confirmed that the high IL-6 concentration in the varicocele and infection groups was concomitant with the increased concentration of both seminal and spermatozoa MDA, indicating an association of this cytokine with LPO, as well as in cells." (PMID 33620706, 2021). "It is noteworthy that the medians of IL-6 concentration in the varicocele and infection groups were approximately 30 pg/mL." (PMID 33620706, 2021). "The underexpressed proteins in bilateral varicocele were mostly included in the inflammation interleukin 6 (IL-6) signaling and inflammation Janus kinase-signal transducer and activator of transcription (Jak-STAT) pathways." (PMID 32987677, 2020). "MAS promotes spermatogenesis in varicocele-induced SD rat, probably by decreasing cytokine (interleukin- 6, and TNF-α) levels, regulating abnormal sex hormones, and decreasing oxidative stress, ER stress and apoptosis." (PMID 31771569, 2019). "MAS promotes spermatogenesis in varicocele-induced SD rat, probably by decreasing cytokines (IL-6, TNF-α) levels, regulating abnormal sex hormones, and decreasing oxidative stress, ER stress, and apoptosis." (PMID 31771569, 2019). "Furthermore, the increased presence of polymorphonuclear and mononuclear immune cells can induce an overexpression of iNos, IL-1, and IL6- in varicoceles." (PMID 36555779, 2022). "By comparing the variables in the groups, we confirmed that a high IL-6 concentration in the varicocele and infection groups was concomitant with an increase of seminal MDA levels, but also with MDA measured in viable spermatozoa, which represents the novelty of this study." (PMID 33620706, 2021). "Seminal IL-6 levels detected both in the infection and varicocele groups resulted in higher than the median of the distribution of the values in the 44 cases analysed (21.5 pg/mL), compared to the very low levels of IL-6 in fertile men." (PMID 33620706, 2021). "With respect to controls, the leucocytospermia and varicocele groups showed significantly increased sperm apoptosis (P = 0.009 and P = 0.011, respectively), IL-6 (P = 0.0001 and P = 0.004, respectively), and TNF-α(P = 0.0001 and P = 0.002, respectively) levels." (PMID 31781347, 2019). "In addition, the induction of varicocele in immature rats could elevate the expression of IL-6 and interferon-gamma in serum and testis tissue." (PMID 37727396, 2023). "On the contrary, the values of IL-6 level, seminal and sperm MDA concentrations were significantly increased in both infection and varicocele groups, compared to those detected in the control group." (PMID 33620706, 2021).
varicocele (continued). "MAS treatment of varicocele-induced group significantly decreased the levels of serum luteinizing hormone (LH) and follicle-stimulating hormone (FSH), as well as testicular interleukin-6 (IL6), tumor necrosis factor-α (TNF-α), ROS/RNS, and malondialdehyde (MDA)." (PMID 31771569, 2019).
alcoholic cirrhosis (13 papers, 1997 to 2025). "In a 2025 study, elevated IL-6 in alcoholic cirrhosis was linked to a modestly increased hazard of decompensation (HR = 1.31 [1.00, 1.71])." (PMID 40969799, 2025). "Previous studies have found that biomarkers for inflammation (Interleukin-6 and Tumor Necrosis Factor α) are elevated in alcoholic cirrhosis patients and predict increasing knee pain in patients with primary osteoarthritis." (PMID 27898694, 2016). "In the study, concentrations of HGF, IL-1α, and IL-6 were analyzed in patients with alcoholic liver cirrhosis classified according to the Child-Pugh scoring system." (PMID 26448742, 2015). "Concentrations of HGF, IL-1α, and IL-6 increase with severity of alcoholic liver cirrhosis, and the concentration of HGF increases with an increase in proinflammatory cytokines concentration." (PMID 26448742, 2015). "The aim of the study was to evaluate concentrations of HGF protein and proinflammatory cytokines IL-1α and IL-6 in serum of patients with different stages of alcoholic liver cirrhosis." (PMID 26448742, 2015). "Patients with alcoholic liver cirrhosis had higher IL-6 in all blood compartments than patients with cryptogenic liver cirrhosis." (PMID 26448742, 2015). "Increased serum TNF-α and IL-6 concentrations have frequently been found in alcoholic liver cirrhosis patients." (PMID 24163503, 2013). "Correlation with IgA serum levels and lymphokine production High IL-6 serum levels and increased production by leukocytes in alcoholic liver cirrhosis." (PMID 15706761, 1997). "In addition, a reduction of circulating levels of PDGF-BB, and increased levels of inflammatory markers such as CRP, IL-6 and TNFα, were observed in patients with alcoholic cirrhosis." (PMID 34884173, 2021). "In the present study, high circulating levels of CRP, IL-6 and TNF-α in the cirrhotic group are consistent with a chronic inflammatory state, which is typical for end-stage alcoholic liver cirrhosis." (PMID 34884173, 2021). "The aim of this study was to determine the relationship between the concentration of selenium and pro-inflammatory and profibrotic cytokines—interleukin-6 (IL-6) and growth differentiation factor 15 (GDF-15) in patients with alcoholic liver cirrhosis." (PMID 28430124, 2017). "The aim of this study was to determine the relationships between the concentration of selenium and pro-inflammatory and profibrotic cytokines—interleukin-6 (IL-6) and growth differentiation factor 15 (GDF-15)—in patients with alcoholic liver cirrhosis." (PMID 28430124, 2017). "According to our best knowledge, relationship between serum concentrations of HGF and serum concentrations of the proinflammatory cytokines (Il-1α, Il-6) in patients with alcoholic cirrhosis has not been described yet." (PMID 26448742, 2015).